KLK1 (kallikrein 1)
Diseases named in the same sentence as KLK1 in open-access papers (continued):
Sharing a sentence is not in itself a finding about the gene and the disease.
colitis (1 paper, 2025). Inflammation of the colon. "This study investigated KLK1's protective function in intestinal barrier integrity using Dextran Sulfate Sodium Salt (DSS) / Azoxymethane (AOM)‐DSS‐induced colitis/CAC models, Apc‐deficient mice, and human clinical samples." (PMID 40859429, 2025). "EGR1 transcription is reduced during colitis, resulting in downregulation of KLK1 in goblet cells, which impairs mucosal barrier integrity and reduces Lys‐des‐Arg9‐BK levels, leading to upregulation of B1R in ADAMDEC1+ fibroblasts." (PMID 40859429, 2025). "The resulting iCAFs promote colorectal cancer progression, highlighting a novel KLK1‐B1R axis linking colitis to tumorigenesis via MAPK signaling." (PMID 40859429, 2025). "KLK1 expression is reduced in colitis, and its potential role in the intestinal mucosal barrier is still unclear." (PMID 40859429, 2025). "In order to confirm the knockdown efficiency of KLK1 in colon tissue, immunofluorescence showed that KLK1 expression was reduced under 2% induced colitis conditions." (PMID 40859429, 2025). "KLK1 has potential application prospects as a drug for the treatment of colitis and inflammation‐related cancers or adenoma carcinoma, and needs further in‐depth research and improvement." (PMID 40859429, 2025). "KLK1‐AAV2 knockdown mice exhibited exacerbated colitis symptoms, including severe diarrhea and impaired mucosal barrier markers, while KLK1 levels are notably reduced in ulcerative colitis patients and colorectal cancer specimens." (PMID 40859429, 2025). "Next, we used the AAV2 (serotype 2) virus to knock down KLK1 in a 2% DSS‐induced colitis model to study its role under inflammatory conditions." (PMID 40859429, 2025). "Here, KLK1 is investigated whether a supplement can reduce colitis and colorectal carcinogenesis." (PMID 40859429, 2025). "This study takes KLK1 as a starting point to explore the specific role of KLK1 in the occurrence of colitis and the development of colorectal cancer, hoping to find new targets for the intestinal epithelial barrier and the treatment of colitis and colorectal cancer." (PMID 40859429, 2025). "To explore the role of KLK1 in the development of colitis, we used a 2% DSS‐induced acute colitis mouse model." (PMID 40859429, 2025). "We used the 2% DSS‐induced acute colitis model in mice, and used 5‐aminosalicylic acid (5‐ASA) as a positive control, which mainly exerts local anti‐inflammatory effects by acting on the intestinal mucosa, to explore the role of recombinant KLK1 (rKLK1) in colitis." (PMID 40859429, 2025).
colorectal cancer (1 paper, 2025). A primary or metastatic malignant neoplasm that affects the colon or rectum. "Notably, Klk1 treatment suppressed these pro‐tumorigenic changes, while the B1R antagonist SSR240612 reversed this effect, highlighting the KLK1‐B1R axis as a potential therapeutic target for inflammation‐associated colorectal cancer." (PMID 40859429, 2025). "In summary, this study mainly revealed the mechanism of action of the KLK1‐[Lys‐des‐Arg9‐BK]‐B1R axis in colorectal cancer." (PMID 40859429, 2025). "On the one hand, the AOM‐DSS model simulates the process of colorectal cancer transformation driven by chronic inflammation, which helps to explore the function of KLK1 in inflammation‐related tumorigenesis." (PMID 40859429, 2025). "In summary, our study revealed that KLK1 plays an important protective role in preventing inflammation‐driven colorectal cancer progression." (PMID 40859429, 2025). "In order to comprehensively evaluate the role of KLK1 in the development and progression of colorectal cancer, we used two classic mouse models." (PMID 40859429, 2025). "KLK1 was highly expressed in normal colon cells (NCM460) but low or absent in colorectal cancer cells (HCT116, SW620)." (PMID 40859429, 2025). "In addition, we collected serum from 272 clinical patients at four stages, including healthy controls (HC), ulcerative colitis (UC), pre‐cancer (PC), and colorectal cancer (CRC) patients, and detected the expression of KLK1 in serum." (PMID 40859429, 2025).
colorectal tumor (1 paper, 2025). "The KLK1‐BDKRB1 axis promotes inflammation‐driven colorectal tumor formation by reprogramming the stromal microenvironment." (PMID 40859429, 2025).
disseminated candidiasis (1 paper, 2016). Systemic candidiasis occurs when Candida yeast enters the bloodstream and may spread (becoming disseminated candidiasis) to other organs, including the central nervous system, kidneys, liver, bones, muscles, joints, spleen, or eyes. "Collectively, these data indicate that IL-17 signaling in the kidney regulates Klk1 expression during disseminated candidiasis." (PMID 27814401, 2016). "To test the hypothesis that Klk1 plays a critical role in IL-17-driven renal protection against disseminated candidiasis, we overexpressed Klk1 with the adenoviral system (Ad-Klk1) and assessed disease susceptibility." (PMID 27814401, 2016). "Thus, IL-17 induces the expression of Klk1 in RTEC following disseminated candidiasis." (PMID 27814401, 2016).
endothelial dysfunction (1 paper, 2022). In vascular diseases, endothelial dysfunction is a systemic pathological state of the endothelium (the inner lining of blood vessels) and can be broadly defined as an imbalance between vasodilating and vasoconstricting substances produced by (or acting on) the endothelium. "After prostate hypoxia and endothelial dysfunction were ameliorated by KLK1, the inflammation-hypoxia vicious cycle was interrupted." (PMID 35154561, 2022). "Intravenous administration of exogenous KLK1 can reduce the inflammatory infiltration of the rat prostate and inhibit chronic inflammatory damage, including hypoxia, oxidative stress, angiogenesis, and fibrosis via ameliorating endothelial dysfunction." (PMID 35154561, 2022).
epilepsy (1 paper, 2015). A brain disorder characterized by episodes of abnormally increased neuronal discharge resulting in transient episodes of sensory or motor neurological dysfunction, or psychic dysfunction. "However, other kallikrein-related peptidases are probably involved in these processes, as can be deduced from the data on overexpression of KLK1 in epilepsy and on the ability of a set of KLKs (KLK1, KLKs 5–7, and KLK9) to promote neural injury." (PMID 26783378, 2015).
erectile dysfunction (1 paper, 2021). Persistent or recurrent inability to achieve or to maintain an erection during sexual activity. "Our previous work verified that KLK1 ameliorated corporal fibrosis via suppressing TGF-β1 and RhoA/ROCK1 pathway in aging-related erectile dysfunction." (PMID 34007408, 2021).
gallbladder cancer (1 paper, 2020). "This is in contrast to the findings of Mingxin, who observed KLK1 expression in gallbladder cancer, especially in female patients." (PMID 33150763, 2020).
glioblastoma (1 paper, 2024). The most malignant astrocytic tumor (WHO grade IV). "Our results show that the mRNA transcripts of KNG-1 and KLK-1 are readily detected in SK-N-MC neuroepithelioma cells, rather than in U87-MG glioblastoma cells." (PMID 39684791, 2024).
gout (1 paper, 2023). A condition characterized by painful swelling of the joints, which is caused by deposition of urate crystals. "Staining of plasma kallikrein K1B and tissue kallikrein KLK1 on blood neutrophils were highest in OA patients with differences observed in OA patients vs. gout patients (p = 0.063 & 0.001 respectively)." (PMID 37202736, 2023). "Patients with OA had higher expression of K1B and KLK1 on blood neutrophils followed by RA and gout patients (both, P < 0.05)." (PMID 37202736, 2023). "On the other hand, OA had higher neutrophil expression of plasma kallikrein (PK) K1B and tissue kallikrein (TK) KLK1 as compared to RA and gout." (PMID 37202736, 2023).
Hyperkalemia (1 paper, 2024). An abnormally increased potassium concentration in the blood. "Furthermore, KLK1 protects against hyperkalemia after a high potassium load in mice." (PMID 38195585, 2024).
inflammatory bowel disease (1 paper, 2025). A spectrum of small and large bowel inflammatory diseases of unknown etiology. "Exploring the therapeutic potential of KLK1 in inflammatory bowel disease (IBD) and developing KLK1‐related drugs is an innovative direction." (PMID 40859429, 2025).
injury (1 paper, 2023). Damage inflicted on the body as the direct or indirect result of an external force, with or without disruption of structural continuity. "The results showed that the methylated KLK1 gene promoter in blood and urine of AKI patients was higher than that of healthy controls in global genomic patterns, and P < 0.0001, indicating that KLK1 gene methylation has the potential to be a marker for monitoring kidney injury." (PMID 37858233, 2023).
Insulin resistance (1 paper, 2014). Increased resistance towards insulin, that is, diminished effectiveness of insulin in reducing blood glucose levels. "In the same rat model, recombinant adeno-associated viral delivery of KLK-1 reversed insulin resistance." (PMID 25100328, 2014). "Previous reports indicate that human KLK-1 generates kinins from kininogens in mice and rats and that delivery of the gene for human KLK-1 into these rodents has beneficial effects on glucose control and insulin resistance." (PMID 25100328, 2014).
lung carcinoma (1 paper, 2025). "Our findings align with recent studies suggesting a causal role for KLK1 in cancer prognosis and carcinogenesis, indicating that drugs targeting KLK1 may offer an avenue for lung cancer prevention." (PMID 41049426, 2025).
nicotine addiction (1 paper, 2024). "In contrast, in the low KLK1 expression subgroup, significantly enriched pathways included nicotine addiction, adolescent-onset type diabetes, linoleic acid metabolism, steroid hormone." (PMID 39606015, 2024).
Parkinson disease (1 paper, 2020). A progressive degenerative disorder of the central nervous system characterized by loss of dopamine producing neurons in the substantia nigra and the presence of Lewy bodies in the substantia nigra and locus coeruleus. "The dysregulation of certain KLKs, that is, KLK1 and KLK7, but mainly KLK6 and KLK8, may contribute to the development of neurodegenerative or neurological disorders such as Alzheimer’s and Parkinson’s diseases, memory disorders or mental illness." (PMID 32655372, 2020).
preeclampsia (1 paper, 2025). Preeclampsia is a hypertensive disorder of pregnancy that is characterized by new-onset hypertension with proteinuria presenting after 20 weeks of gestation, and depending on mild or severe forms may initially present with severe headache, visual disturbances, and hyperreflexia. "Moreover, circulating maternal KLK1 levels are significantly lower in severe preeclampsia than in mild preeclampsia or normal pregnancy, and are negatively correlated with blood pressure and proteinuria." (PMID 41200935, 2025).
psychosis (1 paper, 2026). "In individuals with psychosis, we observed significantly lower levels of KLK1, even after adjusting for potential confounders (effect size -0.25, SE 0.09, FDR 0.049)." (PMID 41535306, 2026).
renal fibrosis (1 paper, 2019). A final common manifestation of a wide variety of chronic kidney diseases characterized by glomerulosclerosis and tubulointerstitial fibrosis. "In this regard, unilateral ureteral obstruction in IL-17 receptor knockout mice showed exacerbated renal fibrosis, increased renal kallikrein-1, and lower neutrophil, but not macrophages, infiltration that were restored by bradykinin treatment." (PMID 31572188, 2019).
subarachnoid hemorrhage (1 paper, 2025). A serious neurological disorder characterized by intracranial hemorrhage into the subarachnoid space. "In the context of ICH, KLK1 has been shown to alleviate cerebral vasospasm in a rabbit model of subarachnoid hemorrhage and to inhibit endothelial cell apoptosis in the basilar artery." (PMID 41322027, 2025).
systemic fungal infection (1 paper, 2018). "Our published study showed that IL-17 activates the kallikrein-kinin system (KKS) through the induction of renal expression of kallikrein 1 (Klk1) during systemic fungal infection." (PMID 30405320, 2018).
type 2 diabetes (1 paper, 2025). "One study reported lower KLK1 protein levels in patients with type 2 diabetes in the pancreatic islet cells, while the mRNA levels of KLK1 were similar to those of healthy subjects." (PMID 41322027, 2025).
uterine corpus endometrial carcinoma (1 paper, 2018). A endometrial carcinoma (disease) that involves the body of uterus. "Furthermore, uterine corpus endometrial carcinoma displayed significant overexpression of KLK12 (3-fold) and downregulation of KLK1 (5-fold), KLK2 (4-fold) and KLK4 (6-fold)." (PMID 29707153, 2018).
tumor (19 papers, 2010 to 2025). "The human kallikrein family comprises 15 homologous, single-chain, secreted trypsin- or chymotrypsin-like serine proteases (KLK1–15) and has been implicated in regulation of tumor growth, neoplastic progression, angiogenesis and metastasis." (PMID 32993568, 2020). "Klk1, Klk21, Klk24 and Klk27 have been linked to Igf1-regulated tumour survival through degradation of the Igf binding protein Igfbp3 in humans." (PMID 21961992, 2011). "KLK1, a member of the Kalinin gene family, can increase extracellular matrix degradation and enhance tumor cells’ survival, proliferation, and invasion." (PMID 36686667, 2022). "The normalized transcript levels of KLK5, 6, 7, 8, 10, 11, and 12 genes were elevated in tumor samples, compared to normal ones while levels of KLK1, 3, 4, 13, and 15 were found to be lower in tumors, compared to normal tissues." (PMID 34065672, 2021). "With respect to tumor growth, KLK1 facilitates EGFR and ERK1/2 cascade activation, which is involved in cell proliferation." (PMID 26783378, 2015). "Mechanistically, loss of Klk1 promoted extracellular matrix (ECM) remodeling by upregulating Mmp2, Mmp9, Fap, decorin, and β‐catenin, thereby promoting epithelial‐mesenchymal transition and tumor progression." (PMID 40859429, 2025). "Furthermore, major MMPs involved in tumor progression (proMMP1, 2, and 9) have been shown to be activated by KLK1, which may lead to enhanced tissue homeostasis or dysregulation." (PMID 32575583, 2020). "For KLK1 ROC curve was significant for all conditions except N+ cases and for BPIFB2 curve was significant for all conditions except N+ cases and late stage of primary tumour cases (T3/T4)." (PMID 33564003, 2021). "KLK1 expression was significantly decreased in recurrent (P = 0.048), non-recurrent (P = 0.03), and both tumor tissues combined (R+NR) compared with healthy tissues (P = 0.007)." (PMID 33150763, 2020). "The mean percent tumor core stained for KLK1, KLK7, KLK9 or KLK10 across grades III and IV were not significantly different." (PMID 26231762, 2015). "Similarly, KLK1, KLK2, and KLK3 can regulate tumor growth through IGF-binding protein (IGFBP) degradation, thereby allowing the release of the insulin-like growth factors (IGFs) and proliferative signals." (PMID 26783378, 2015).
cancer (16 papers, 2011 to 2025). A tumor composed of atypical neoplastic, often pleomorphic cells that invade other tissues. "Kallikrein-related peptidase 10 KLK1, a serine protease which is implicated in carcinogenesis and may potentially serve as a novel cancer and other disease biomarkers." (PMID 26515461, 2016). "Although this study revealed the key role of the KLK1‐B1R axis in intestinal barrier protection and inflammatory‐cancer transformation, there are still several limitations: 1) The controversy over the function of B1R has not been fully resolved." (PMID 40859429, 2025). "In comparison to pancreatic juices obtained from PDAC patients with noncancerous controls, a previous study recognized some differential proteins in cancer samples like kallikrein 1 (Klk1)." (PMID 35180880, 2022). "All fifteen members of the kallikrein family (KLK1-15) had their expression analyzed in fifteen different cancer types using the gene expression data from TCGA." (PMID 29707153, 2018). "The 8 cell types were annotated based on the differentially expressed markers: Bnip3 for autophagic cancer cells, Mki67 for proliferating cancer cells, Cd14, Apoe, C1qc, Mrc1, Lyz2 for monocytes, Col3a1 for fibroblasts, Cd3e and Gzma for T cells, Flt1 for endothelial cells, and Klk1 for DCs." (PMID 38802348, 2024). "Differential expression of KLK1 has been identified in several cancers and other diseases." (PMID 24586431, 2014). "AZGP1, BPIFB2 and KLK1 were significantly downregulated in our data of which role of KLK1 and AZGP1 is well reported in cancer but BPIFB2 remains unexplored." (PMID 33564003, 2021).
cardiovascular diseases (4 papers, 2014 to 2025). "Another promising target for the genetic modification of SCs is the human tissue kallikrein (KLK1) gene with a proven protective role in cardiovascular disease both in vitro and in vivo." (PMID 30544622, 2018). "KLK1 is a key component of the kallikrein-kinin system and may activate protease activated receptors (PARs) in inflammatory and cardiovascular diseases." (PMID 29348876, 2017). "Although most of the biological functions of KLK1 are mediated by kinin receptor signaling, recent studies suggest that KLK1 may also activate protease activated receptors (PARs) in inflammatory and cardiovascular diseases." (PMID 24586431, 2014).
infection (2 papers, 2016 to 2024). The state of being infected such as from the introduction of a foreign agent such as serum, vaccine, antigenic substance or organism. "Through the integrated analysis of miRNA-mRNA expression profiles, it was found that the expression of FOXN4, MUC4, KLK1 and CD163 were up-regulated under the action of miR-106b-3p after infection." (PMID 38178220, 2024).
KLK1 also shares sentences with these, for which no sentence is quoted: chronic kidney disease (2 papers); Colorectal (2); fibrosis (2); ischemic stroke (2); myocardial ischemia (2); neurological disorders (2); viral infections (2); acute pancreatitis (1); aortic aneurysm (1); cardiomyopathy (1); cerebrovascular disorder (1); colon adenocarcinoma (1); colon adenoma (1); colorectal adenoma (1); dermatitis (1); diabetic retinopathy (1); enteritis (1); essential hypertension (1); gastric neoplasm (1); head and neck cancer (1); hyperinsulinism (1); hyperlipidemia (1); kidney injury (1); malignant brain tumors (1); melanoma (1); mental illness (1); metabolic syndrome (1); multiple myeloma (1); nasopharyngeal carcinoma (1); neuropathy (1).
A further 11 diseases each share a sentence with KLK1 in 1 paper.